CX3CR1 (C-X3-C motif chemokine receptor 1)
Diseases named in the same sentence as CX3CR1 in open-access papers (continued):
Sharing a sentence is not in itself a finding about the gene and the disease.
osteoporosis (9 papers, 2019 to 2025). A condition of reduced bone mass, with decreased cortical thickness and a decrease in the number and size of the trabeculae of cancellous bone (but normal chemical composition), resulting in increased fracture incidence. "Numerous studies have confirmed that the Cx3cr1 activity is closely associated with the pathogenesis of osteoporosis." (PMID 41208866, 2025). "For example, by inhibiting CX3CL1 or its receptor CX3CR1, the formation and activity of osteoclasts can be reduced, thereby slowing bone loss, which is important for the treatment of skeletal diseases such as osteoporosis." (PMID 41416066, 2025). "However, further investigation is required to elucidate the specific roles and mechanisms of Cx3cr1+iOCs in delayed healing associated with osteoporosis." (PMID 39223264, 2024). "Recent research has found that in osteoporosis, some osteoclasts, termed inflammatory osteoclasts (iOCs), show high expression of Cx3cr1." (PMID 39223264, 2024). "Regarding the fact that acting against the CX3CL1/CX3CR1 axis is a potential target of immune treatment in osteoporosis, the number of available papers tackling the topic is certainly insufficient." (PMID 31780870, 2019). "Cx3cr1 is expressed in osteoclast precursors, implying that CX3CL1/CX3CR1 signaling can regulate osteoclast differentiation and thus affect the development of osteoporosis." (PMID 36245484, 2022). "The experiment may indicate a possible correlation between the CX3CL1/CX3CR1 axis and LPA/LPAR1 in the promotion of osteoclastogenesis processes, at the same time indicating the use of LPA antagonists to be a highly promising direction in the treatment of osteoporosis." (PMID 31780870, 2019).
pancreatic ductal adenocarcinoma (9 papers, 2012 to 2024). An infiltrating adenocarcinoma that arises from the epithelial cells of the pancreas. "Probably for this reason, the simultaneous increase in CX3CL1 and CX3CR1 expression would lead to a worse prognosis in patients with pancreatic ductal adenocarcinoma." (PMID 32466280, 2020). "CX3CR1 is normally expressed by hematopoetic cells, prostate cancer, breast cancer and pancreatic ductal adenocarcinoma (PDAC)." (PMID 22952674, 2012). "CX3CR1 is an important chemokine receptor and regulates the chemotactic migration of pancreatic ductal adenocarcinoma (PDAC) cells." (PMID 22952674, 2012). "Moreover, human pancreatic ductal adenocarcinoma (PDAC) cells express CX3CR1 and CX3CL1 abundantly and the CX3CR1/CX3CL1 axis can regulate intraneural invasion of PDAC." (PMID 24966464, 2014). "High CX3CR1 expression or high expression of the CX3CL1/CX3CR1 axis were also independent negative prognostic factors in pancreatic ductal adenocarcinoma." (PMID 38731899, 2024). "For example, patients with a high expression of CX3CR1 were reported to be an independent negative prognosis factor in pancreatic ductal adenocarcinoma." (PMID 35140706, 2021). "For example, one study showed that TGF-β does not change the CX3CR1 expression level in pancreatic ductal adenocarcinoma cells." (PMID 32466280, 2020).
Anxiety (8 papers, 2018 to 2024). Intense feelings of nervousness, tension, or panic often arise in response to interpersonal stresses. "Cx3cr1-/- knockout mice exhibit the hyperactive phenotype, a deficiency associated with impaired long-lasting connectivity and social behaviour, and changes in fear and anxiety." (PMID 32664639, 2020). "However, conditional deletion of TNF from microglia using CX3CR1-Cre prevented the increase in anxiety-like behavior in stressed CX3CR1-Cre positive mice relative to their unstressed CX3CR1-Cre expressing littermates, although there was a baseline behavioural shift in these animals." (PMID 36104437, 2022). "Deficiency in CX3CR1 or CCR2, did not affect the increase of Ly6Chi monocytes in the blood after social disruption stress, but prevented brain infiltration of CD45hi CD11b+ macrophages and the development of stress-induced anxiety." (PMID 30057531, 2018).
autoimmune disease (8 papers, 2006 to 2025). A disorder resulting from loss of function or tissue destruction of an organ or multiple organs, arising from humoral or cellular immune responses of the individual to their own tissue constituents. "CX3CL1, the only member of the CX3C chemokine family, and its sole receptor, CX3CR1, are involved in the recruitment of monocytes/Mφ and lymphocytes, playing crucial roles in various autoimmune diseases." (PMID 39497829, 2024). "Although the importance of the FKN‐CX3CL1/CX3CR1 axis in neurological and autoimmune diseases is well established, little is known about the interaction between CX3CL1 and other CX3CR1 ligands whose expression is also increased in inflammatory processes such as periodontitis." (PMID 38415821, 2024). "CX3CR1 levels were also not significantly different in sorted CD5−CD163+CD14-positive and CD14-negative DC3s from patients with autoimmune diseases, further indicating that CX3CR1 expression in CD1c+ DCs may be independent from CD14 expression in CD1c+ DCs." (PMID 37042831, 2023). "An increased level of CX3CR1 in systemic sclerosis may help to recruit immune cells to the site of inflammation, giving CX3CR1 an important role in the pathogenesis and development of inflammatory response in autoimmune diseases." (PMID 33691643, 2021).
diabetic retinopathy (8 papers, 2015 to 2025). "In this case Cx3cr1 deficiency activated microglia, enhanced the inflammatory response, disrupted the vascular integrity and accelerated the progression of diabetic retinopathy." (PMID 39996770, 2025). "Studies of CX3CR1-KO and CX3CL1-KO mice reveal that a disrupted CX3CR1/CX3CL1 signaling pathway exacerbates diabetic retinopathy damage through microglial activation, neuronal cell loss, and vascular impairment." (PMID 39940727, 2025). "The aim of this study is to determine the role of CX3CR1 in inflammatory-mediated damage to retinal neurons using a model of diabetic retinopathy." (PMID 26514658, 2015). "Overview of studies on fractalkine/CX3CR1 pathway in diabetic retinopathy." (PMID 39796231, 2025). "Summary of proposed mechanisms of fractalkine/CX3CR1 pathway in diabetic retinopathy." (PMID 39796231, 2025). "Additionally, the positive effects of microglia depletion in models of diabetic retinopathy appear to depend on CX3CR1." (PMID 39940727, 2025).
HIV-1 infection (8 papers, 2009 to 2024). The type species of lentivirus and the etiologic agent of acquired immunodeficiency syndrome (AIDS). "The increased expression of CX3CR1 on monocytes has been associated with systemic inflammation during HIV-1 infection." (PMID 32626718, 2020). "CCR2-64I (A/A genotype) and SDF1-3'A are also known to protect against HIV infection, while CX3CR1 expression is associated with an increased risk of HIV-1 infection." (PMID 30998710, 2019). "CX3CL1 and its receptor CX3CR1 have received increased attention regarding their roles in HIV-1 infection and in HAND specifically." (PMID 24147028, 2013). "Using this monocyte phenotyping panel we found that in untreated HIV-1 infection there is lower density of CCR2 on inflammatory monocytes and lower expression of CX3CR1 on patrolling monocytes." (PMID 26430882, 2015). "In summary, we have identified distinct perturbations in circulating monocyte phenotypes in patients with untreated HIV-1 infection: elevated expression of HLA-DR and CD86 that normalized with ART while expression of the chemokine receptors CX3CR1 and CCR2 rose with ART." (PMID 26430882, 2015).
injury (8 papers, 2014 to 2025). Damage inflicted on the body as the direct or indirect result of an external force, with or without disruption of structural continuity. "In a model of kainic acid-induced excitotoxic brain injury, the Ly6Clo, CX3CR1+ monocytes migrate to the injured brain and reduce neurological disability and neuronal degeneration, suggesting these monocytes have a role in neuroprotection." (PMID 25469644, 2014). "NUDT21 depletion in CX3CR1-expressing cells exacerbates LPS-induced Lung Injury." (PMID 41282183, 2025). "In addition, mouse Cx3cr1-mediated control of NC monocyte levels has more recently been suggested to modulate the innate immune response to traumatic brain injury." (PMID 37464408, 2023). "Our results indicate that the neuroprotective effects of TNF-α-hNPCs in HI brain injury could be provided by stimulation of microglial CX3CR1 expression, as well as direct release of CX3CL1." (PMID 32403417, 2020). "In the light of this analysis, it is difficult to state whether GC modulation of the CX3CL1/CX3CR1 axis is a neuroprotective or neurotoxic therapeutic option in case of CNS trauma." (PMID 26927660, 2017).
non-small cell lung carcinoma (8 papers, 2021 to 2025). A group of at least three distinct histological types of lung cancer, including non-small cell squamous cell carcinoma, adenocarcinoma, and large cell carcinoma. "Additionally, ADAR1 loss strengthens the sensitivity of non-small cell lung cancer cells to anlotinib through modulating CX3CR1-fractalkine expression." (PMID 38468359, 2024). "Recent findings in non-small cell lung cancer (NSCLC) patients demonstrated a higher proportion of CX3CR1+ CD8+ T cells in peripheral blood compared to tumor tissue." (PMID 41149503, 2025). "The same study observed a higher frequency of the CX3CR1+ subset on circulating CD8+ T cells shortly after treatment initiation in patients with non-small-cell lung cancer (NSCLC) treated with anti-PD-1." (PMID 39273452, 2024). "Notably, CX3CR1 expression shortly after immune checkpoint blockade is a positive predictive marker of response and survival in patients with non-small cell lung cancer." (PMID 39481389, 2024). "Here the authors show that effective ICI therapy correlates with increased frequency of circulating CX3CR1+CD8+ T cells in preclinical tumor models and in a cohort of patients with non-small cell lung cancer treated with anti-PD-1." (PMID 33658501, 2021). "Furthermore, their study evidenced that the early surge in CX3CR1+ subset frequency among circulating CD8+ T cells was correlated to both responses by and prolonged survival of non-small cell lung cancer patients undergoing anti-PD-1 therapy." (PMID 38139364, 2023). "Furthermore, an increase in the frequency of the CX3CR1+ subset in circulating CD8+ T cells early after initiation of anti-PD-1 therapy correlates with response and survival in patients with non-small cell lung cancer." (PMID 33658501, 2021).
pulmonary hypertension (8 papers, 2005 to 2024). Increased pressure within the pulmonary circulation due to lung or heart disorder. "Variations in the gene encoding the CX3CR1 have been identified as individual susceptibility factors associated with SSc and SSc-pulmonary arterial hypertension (PAH)." (PMID 30072999, 2018). "Additionally, CX3CR1 polymorphism was also seen in association with pulmonary arterial hypertension." (PMID 39392260, 2024). "As an immune-related hub gene, CX3CR1 presents with a promising ability to be used to distinguish between patients with pulmonary hypertension caused by various reasons and those in the control group and can be considered a potential biomarker of pulmonary hypertension." (PMID 34252346, 2021). "In pulmonary arterial hypertension, T cells upregulated the exhibition of CX3CR1 elevated plasma FKN concentrations, and increased FKN mRNA and protein product in pulmonary artery endothelial cells were brought to observation." (PMID 39392260, 2024). "Previous studies have also reported that CX3CR1 plays an important role in the polarization of macrophages, which is essential in the development of pulmonary hypertension." (PMID 36246557, 2022). "CX3CR1 is an important regulatory target and potential biomarker in pulmonary arterial hypertension." (PMID 34252346, 2021). "Fractalkine (FKN) and its receptor CX3CR1 are critical mediators in thevascular and tissue damage of several chronic diseases, including systemicsclerosis (SSc) and pulmonary arterial hypertension (PAH)." (PMID 16584113, 2005). "The inflammatory mechanism of chemokine, fractalkine, and its receptor, Cx3CR1, in the lungs of patients with pulmonary hypertension may play a role in the natural development of pulmonary hypertension, proving the possibility of an inflammatory component in pulmonary hypertension." (PMID 36611783, 2023).
AIDS (7 papers, 2011 to 2024). A syndrome resulting from the acquired deficiency of cellular immunity caused by the human immunodeficiency virus (HIV). "Thus, CX3CR1 is a key recessive genetic risk factor for HIV/AIDS." (PMID 38674036, 2024). "Some studies also showed that genetic variants on CX3CR1 were associated with HIV susceptibility and rapid HIV progression to AIDS." (PMID 32928285, 2020). "Genotypes of exonic polymorphisms in chemokine coreceptor genes CCR3, CCRL2 and CXCR6 on Chromosome 3p21 and in CCR8 and CX3CR1 on 3p22 were tested for their genetic influence on AIDS progression." (PMID 22046140, 2011). "The possible role of two non-synonymous SNPs, CX3CR1-V249I (rs3732379), and CX3CR1-T280M (rs3732378), in HIV progression to AIDS remains controversial." (PMID 24167505, 2013).
brain injury (7 papers, 2014 to 2025). Acute and chronic (see also brain INJURIES, CHRONIC) injuries to the brain, including the cerebral hemispheres, CEREBELLUM, and brain STEM. "CX3CL1/CX3CR1 is an important pathway involved in the crosstalk between neurons and microglia, which functions differentially in acute and chronic brain injuries." (PMID 37234914, 2023). "In the current study, we investigated whether peripheral leukocytes infiltrated the brain following mild traumatic brain injury (mTBI) using a CX3CR1- and CCR2-double transgenic reporter mouse model." (PMID 41574049, 2025). "Collectively, these studies underscore a role for CX3CR1 signaling in response to CNS injury and suggest that mechanisms by which CX3CR1 promotes neuroprotection during the acute phase of brain injury include a protective microglia phenotype and reduced monocyte/macrophage recruitment." (PMID 26329692, 2015). "Our results suggest that inhibition of CX3CR1 signaling could function as a therapeutic modality in ischemic brain injury, by reducing recruitment of peripheral macrophages and expansion/activation of CNS microglia and macrophages, resulting in protection of neurological function." (PMID 24490760, 2014). "In the absence of brain injury, the fractalkine/CX3CR1 axis may reduce the microglial activation and regulate proper neurogenesis and memory processes." (PMID 33498837, 2021).
colon carcinoma (7 papers, 2013 to 2024). "CX3CR1 deficient mice show a reduction in tumor infiltrating macrophages in SL4 colon carcinoma and skin cancer model." (PMID 37771579, 2023). "Thus, CX3CR1 expression is associated with the aggressiveness of human colon cancer." (PMID 24245985, 2013). "For example, in colon carcinoma CT26 engineered to express CX3CR1, the use of an FKN–CX3CR1 blocking antibody in combination with anti-PD-1 results in enhanced therapeutic activities." (PMID 39125578, 2024). "In combination with anti-PD-1 immunotherapy, this CX3CR1 monoclonal antibody enhances survival in an immunocompetent mouse colon carcinoma model through a decrease in tumor-promoting myeloid populations." (PMID 37771579, 2023). "In this study, we found that CX3CR1 was expressed in human colon carcinomas in a histologic grade- and stage-dependent manner, and CX3CR1 upregulation in TAMs was correlated with poor prognosis." (PMID 24245985, 2013). "To investigate the role of CX3CR1 in tumor development of colon carcinoma cells in the liver, we injected CX3CR1−/− mice and WT controls with SL4 cells intrasplenically." (PMID 24245985, 2013). "CX3CR1 expression was significantly elevated in poorly differentiated colon carcinoma, which was much higher than that of moderately differentiated or well-differentiated colon carcinoma." (PMID 24245985, 2013). "Our study showed that enhanced CX3CR1 expression was correlated with the poor prognosis in human colon carcinoma." (PMID 24245985, 2013). "CX3CR1-positive cells within the area colocalized with CD68-positive macrophages, indicating a high concordance of CD68 and CX3CR1 expression in human primary colon carcinoma during malignant progression." (PMID 24245985, 2013). "To understand the role of CX3CR1 in macrophage survival during hepatic metastasis of colon cancer, we cocultured macrophages derived from CX3CR1−/− or WT mice with murine SL4 colon cancer cells in a 3D peptide gel." (PMID 24245985, 2013). "To further analyze the expression of CX3CR1 in the tumor stroma, we utilized a murine model in which mouse colon cancer cells (SL4) were injected into the spleen and tumors developed in the liver." (PMID 24245985, 2013). "In this study, we observed that colon carcinoma patients at more advanced clinical stages, those with lymph node or liver involvements, and those who had recurrence within 3 years displayed markedly higher CX3CR1 expression levels." (PMID 24245985, 2013). "Moreover, analysis of CX3CR1 expression in primary tumors and formation of metastases revealed that patients who had advanced clinical stage disease, metastasis, or recurrent lesion within 3 years showed increased CX3CR1 expression in colon cancer tissue." (PMID 24245985, 2013). "It has also been recently shown that CX3CR1, the receptor for CX3CL1, is functionally required in TAMs to support angiogenesis and efficient formation of colon cancer liver metastases." (PMID 25882816, 2015). "Additionally, CX3CL1/CX3CR1 signaling induces paclitaxel resistance in gastric cancer through RhoA signaling and promotes migration and resistance to anti-PD-1 therapy in colon cancer, and the blockade of CX3CL1/CX3CR1 has proven effective in both cases." (PMID 39409924, 2024). "Furthermore, we showed that in a microenvironment lacking CX3CR1, the liver metastasis of colon cancer cells was significantly inhibited." (PMID 24245985, 2013). "In mice lacking CX3CR1, the liver metastasis of colon cancer cells was significantly inhibited." (PMID 24245985, 2013).
Crohn disease (7 papers, 2010 to 2022). A gastrointestinal disorder characterized by chronic inflammation involving all layers of the intestinal wall, noncaseating granulomas affecting the intestinal wall and regional lymph nodes, and transmural fibrosis. "A coding polymorphism in CX3CR1 in patients with Crohn’s disease was associated with impaired ability to produce antibodies against multiple gut fungal species." (PMID 29801518, 2018). "Importantly, their study further demonstrated that SNPs in the gene encoding CX3CR1 are strongly associated with IgG responses against fungi in patients with Crohn’s diseases." (PMID 31969481, 2020). "Whether targeting specific cell types such as CX3CR1+ MNPs to generate effective antibody responses against pathogenic fungi would be effective in Crohn’s disease patients remains a question for future studies." (PMID 29801518, 2018). "Furthermore, CD14+CCR2+CX3CR1+ monocyte-derived intestinal MPs can elicit the activation of IFN-γ-producing CD3−CD56+NKp46+NKp44− group 1 ILCs from Crohn's disease patients." (PMID 26269452, 2015).
diabetic nephropathy (7 papers, 2019 to 2025). "CX3CR1 was shown to be potentially useful as a diagnostic marker for diabetic nephropathy and a predictor of disease progression." (PMID 40508161, 2025). "The CX3CL1/CX3CR1 axis directly upregulates the expansion of mesangial cells in diabetes nephropathy through ROS and MAPK." (PMID 36969169, 2023). "Also, it is reported that the CX3CL1/CX3CR1 axis can up-regulate mesangial cell expansion directly via Reactive Oxygen Species (ROS) and Mitogen-Activated Protein Kinase (MAPK) in diabetic nephropathy (Park, Song & Ha, 2012)." (PMID 31355054, 2019).